HGF (hepatocyte growth factor)
Diseases named in the same sentence as HGF in open-access papers (continued):
Sharing a sentence is not in itself a finding about the gene and the disease.
Sepsis (21 papers, 2012 to 2025). Sepsis is defined as life-threatening organ dysfunction caused by a dysregulated host response to infection. "In adults, higher plasma levels of HGF in patients with sepsis, has been associated with a poorer prognosis." (PMID 38001236, 2024). "Intravenous injection of recombinant HGF into mice can alleviate mice’s lung endothelial pyroptosis caused by sepsis of various microorganisms and improve lung endothelial injury and acute lung injury." (PMID 36776394, 2022). "Recombinant HGF was intravenously injected into mice with sepsis caused by caecal ligation puncture (CLP)." (PMID 32795289, 2020). "In this process, HGF prevented the sepsis-induced loss of thrombomodulin, a key endothelial molecule that counteracts DIC formation." (PMID 22536224, 2012). "Using LPS- and D-galactosamine (GalN-) treated mice as a “lethal” model of sepsis, we found that an early induction of anti-apoptotic molecule (such as Bcl-xL) by recombinant HGF leads to the inhibition of massive hepatocyte loss and hepatic dysfunction." (PMID 22536224, 2012). "Third, while our data indicate that 3D‐EVs can effectively ameliorate sepsis‐ALI via HGF delivery, further investigation is needed to reveal the specific mechanisms and identify alternative substances playing therapeutic roles in EVs." (PMID 40041965, 2025). "These cumulative results indicate that 3D‐EVs can partly reverse sepsis‐induced down‐regulation of the PI3K/AKT pathway in mouse lung by delivering HGF and thus ameliorating lung injury." (PMID 40041965, 2025). "In this study, we identified 8 senescence-related genes (IGFBP7, GMFG, IL10, IL18, ETS2, HGF, CD55, and MMP9) and developed a diagnostic model for the prediction of sepsis occurrence." (PMID 38259686, 2023). "A comprehensive analysis was conducted to investigate the impact of senescence-related genes on sepsis, and 8 hub genes (IGFBP7, GMFG, IL10, IL18, ETS2, HGF, CD55, MMP9) associated with senescence were identified." (PMID 38259686, 2023). "Previous studies have demonstrated LPS-induced organ damage and elevated plasma HGF levels in rodents with systemic inflammatory response syndrome and early sepsis." (PMID 36776394, 2022). "It is also reported in a prospective observational study that elevated plasma HGF level is an indicator of poor prognosis in sepsis patients." (PMID 35615364, 2022). "The results of our study demonstrated that HGF effectively ameliorates sepsis-induced acute lung injury and pulmonary vascular endothelial injury." (PMID 32795289, 2020). "Several lines of clinical evidence have demonstrated that blood HGF levels raised in response to organ damage in patients with sepsis in the early phase." (PMID 32795289, 2020). "To validate this notion, we measured the serum HGF levels in the patients with sepsis and those with PICs after esophagectomy for esophageal cancer in the clinical settings." (PMID 32630328, 2020). "Here, we demonstrated that HGF alleviates polymicrobial sepsis-induced lung injury and inflammation and improves the survival rate of septic mice." (PMID 32795289, 2020). "To explore the effect of HGF on acute lung injury (ALI) in sepsis, we intravenously injected recombinant HGF into mice with sepsis caused by caecal ligation puncture (CLP)." (PMID 32795289, 2020). "The recombinant HGF intravenously administration mitigates polymicrobial sepsis-induced pulmonary vascular endothelial pyroptosis, attenuates pulmonary vascular endothelial injury and acute lung injury in mice." (PMID 32795289, 2020). "Compared to CLP alone, HGF treatment dramatically abated the inflammation and alleviated the lung injury induced by polymicrobial sepsis." (PMID 32795289, 2020). "Previous studies have illustrated that HGF alleviates acute kidney injury and acute hepatic injury in mice with LPS-induced sepsis." (PMID 32795289, 2020). "This study first showed that patients with sepsis and PICs after esophagectomy had elevated serum HGF levels in the clinical setting." (PMID 32630328, 2020).
Sepsis (continued). "Enhancement of endogenous HGF response for minimizing septic tissue injuries, however, secretion of HGF seems insufficient in sepsis, with a time lag between the injury and HGF increasing." (PMID 32795289, 2020). "One of the most key results related to novel functions of HGF during sepsis is that HGF directly targets immune cells, including macrophages and lymphocytes that highly express HGF-receptor, c-Met, under inflammatory conditions." (PMID 22536224, 2012). "There is now ample evidence to show the protective effects of HGF during experimental sepsis in animal models." (PMID 22536224, 2012). "In a rat model of sepsis, enhancement of HGF production was insufficient, with a time lag, after an endotoxic challenge (i.e., 3-fold increase at 12 hours after LPS treatment), associated with the onset of septic hepatitis." (PMID 22536224, 2012). "The present paper focuses on both the emerging roles of HGF in sepsis and the therapeutic potential of HGF-c-Met signaling to prevent or reverse MOF-related pathological conditions." (PMID 22536224, 2012). "IL-6 is responsible for thrombosis during sepsis, while HGF potently inhibits IL-6 production in LPS-primed macrophages." (PMID 22536224, 2012). "We and other groups have accumulated evidence to show that HGF, an intrinsic anti-inflammatory regulator, is useful to inhibit or reverse sepsis-induced hepatitis, ARDS, and acute renal failure (ARF) at least in animal models." (PMID 22536224, 2012). "During sepsis, plasma HGF levels gradually increase in septic patients, while macrophages acquire high levels of c-Met in vitro and in vivo (animal models)." (PMID 22536224, 2012). "Such direct anti-inflammatory effects of HGF are considered to be the key mechanism whereby HGF inhibits cytokine storm in an initial stage of sepsis." (PMID 22536224, 2012). "HGF will be a promising adjuvant therapy strategy for treating sepsis and acute lung injury." (PMID 36776394, 2022). "For example, HGF reportedly protects mitochondrial physiology by activating mammalian target of rapamycin signaling to partially ameliorate endothelial pyroptosis and attenuate vascular endothelial injury and acute lung injury in an animal model of sepsis." (PMID 35615364, 2022). "In addition, HGF is substantially produced during surgical trauma and infectious stress such as sepsis, and plays an important role as a powerful mediator to induce protective effects against damaged tissues after surgical stress." (PMID 32630328, 2020). "However, for clinical treatment of sepsis with HGF, clinical studies are necessary, the dose and timing of HGF administration should be determined according to its pharmacokinetics and pharmacodynamics in patients." (PMID 32795289, 2020). "HGF may have the potential to be a promising adjuvant therapeutic strategy aimed at the treatment of sepsis and acute lung injury." (PMID 32795289, 2020). "Although the effect of HGF on clinical sepsis patients is speculative and remains to be elucidated, it is tempting to believe that it could be a promising adjuvant therapy for sepsis." (PMID 32795289, 2020). "The effect of HGF in attenuating vascular endothelial injury could alleviate acute lung injury in sepsis and improve the prognosis of sepsis, at least in animal model." (PMID 32795289, 2020). "Moreover, the HGF/c-Met signaling pathway directly contributed to the promotion of liver metastasis during sepsis in the animal model." (PMID 32630328, 2020). "Besides systemic lupus erythematosus, several acute systemic inflammatory diseases like systemic inflammatory response syndrome and sepsis show altered plasma levels of both HGF and IL-1β." (PMID 31068815, 2019). "Elevated HGF level in sepsis patients is a predictor of mortality." (PMID 30890150, 2019). "Based on these data, we emphasized that HGF may have the potential to inhibit fulminant hepatic failure during sepsis via its potent anti-apoptotic action." (PMID 22536224, 2012).
Sepsis (continued). "Given that cytokine storm is responsible for coagulation and inflammation during sepsis, therapeutic effect of recombinant HGF may be due to the possible down-regulation of proinflammatory cytokines." (PMID 22536224, 2012). "Sepsis-mediated upregulation of HGF is suggested to be an effort to minimize the manifestation of MOF, but this response may be transient, delayed and sometimes insufficient, during progression of septic MOF." (PMID 22536224, 2012). "Given that HGF is protective during sepsis, the increase of blood HGF may be interpreted as a compensated response, rather than a risk factor." (PMID 22536224, 2012). "These biological activities may also contribute to HGF-induced anti-inflammatory outcomes during sepsis." (PMID 22536224, 2012). "Therefore, this experimental result indicates that HGF supplement therapy might be available for improving sepsis-induced organ damage." (PMID 32795289, 2020). "Thus, HGF may be a candidate for the therapeutic development of septic diseases, and large clinical studies are necessary to understand the regulation of HGF in humans before proposing HGF as a new drug target in such a complex system as sepsis." (PMID 22536224, 2012). "Thus, both pathways are important for HGF-mediated protection during sepsis." (PMID 22536224, 2012). "Overall, 3D‐EVs effectively ameliorate sepsis‐induced ALI and enhance prognosis by enriching and delivering HGF, suggesting that their application represents a promising treatment strategy for septic ALI." (PMID 40041965, 2025). "Consensus cluster analysis we successfully classified sepsis patients into two distinct groups based on the expression of 8 hub genes (IGFBP7, GMFG, IL10, IL18, ETS2, HGF, CD55, and MMP9)." (PMID 38259686, 2023). "Hepatocyte growth factor (HGF), IL-7, IL-15, IL-22, Ac2-26, Vaspin, Hsp22, and adiponectin (APN) exhibit anti-apoptotic functions in the prevention and treatment of sepsis." (PMID 37629199, 2023). "Therefore, HGF may be a promising supplemental therapy to ameliorate sepsis-induced organ damage." (PMID 32795289, 2020). "Hepatocyte growth factor (HGF) is a multifunctional protein involved in endothelial cell injury and plays a pivotal role in sepsis." (PMID 30890150, 2019). "Moreover, interesting work has been undertaken on therapeutic factors, such as Ang-1, KGF, and HGF, in ARDS and sepsis." (PMID 34659231, 2021). "Although hepatocyte growth factor (HGF) has been shown to have anti-apoptotic and anti-necrotic effects, whether it prevents pyroptosis to improve endothelial injury in sepsis remains unclear." (PMID 32795289, 2020). "In this study, patients with sepsis and PIC had higher serum HGF levels in the clinical setting." (PMID 32630328, 2020). "In addition, a marked increase in cell growth-modulating factors (such as HGF, FGFβ, HB-EGF, and KGF) in the circulation of severe sepsis patients was also found." (PMID 25882865, 2015). "Endothelial injury and lung injury were not fully reversed by HGF, probably due to the complex pathophysiological mechanism of polymicrobial sepsis and the subsequent injury induced by persistent inflammation, nor did recombinant HGF rescue all of septic mice in previous researches." (PMID 32795289, 2020). "Moreover, it was found that the HGF level was significantly higher in sepsis patients than in the SIRS groups without infection, which correlates with our results." (PMID 25928796, 2015). "This experimental result indicates that HGF supplement therapy might be available for inhibiting not only ARDS but also septic ARF, an important lethal factor of sepsis-induced MOF." (PMID 22536224, 2012).
triple-negative breast carcinoma (21 papers, 2012 to 2025). An invasive breast carcinoma which is negative for expression of estrogen receptor (ER), progesterone receptor (PR), and human epidermal growth factor receptor 2 (HER2). "Among IHC-based subtypes, HGF positivity was strongly associated with triple-negative breast cancer, with 82% of these tumors having HGF positivity compared to 13% in non-TNBC [RFD = + 65.85, 95% CI (61.71, 69.98)." (PMID 34344422, 2021). "In triple-negative breast cancer, oleuropein inhibits cell migration and invasion induced by HGF through autophagy by upregulation of LC3-II/LC3-I and Beclin-1, as well as downregulation of p62." (PMID 39203892, 2024). "And another study demonstrated that lower baseline plasma HGF are potential biomarkers for anti-angiogenesis therapy and immunotherapy in advanced triple-negative breast cancer patients." (PMID 38776028, 2024). "Although HGF-positive tumors were highly prevalent among triple-negative breast cancer; it was a defining feature among Basal-like tumors." (PMID 34344422, 2021). "In addition, Timo AIII decreased mRNA expression of MMP-9 in human pancreatic cancer cell AsPC-1 and suppressed HGF-induced MMP-9 expression in triple negative breast cancer cell MDA-MB-231." (PMID 32581782, 2020). "In a previous clinical study, foretinib was shown to have anti-cancer activity in triple-negative breast cancer with the low amplification of Met; foretinib has exerts anti-cancer effects through the inhibition of several pathways, in addition to the HGF/Met pathway." (PMID 29854314, 2018). "We have also used MAME as a preclinical model to test the effects of cabozantinib on the tumor-promoting interactions between different triple-negative breast cancer cells, representing various molecular subtypes of the disease, and CAFs and normal fibroblasts overexpressing HGF." (PMID 28506312, 2017). "In addition to TGF-β, a number of factors and ligands are involved in drug resistance in triple-negative breast cancers, for instance, hepatocyte growth factor (HGF) could activate Met and induce metabolic reprogramming." (PMID 35395809, 2022). "Timo AIII concentration-dependently inhibited HGF-induced cell migration and invasion which were blocked by COX2 inhibitor NS398 and ERK inhibitor PD98059 in triple negative breast cancer cell MDA-MB-231." (PMID 32581782, 2020). "Here we demonstrate that fibroblast secretion of HGF activates Met and leads to EGFR/Met crosstalk and resistance to EGFR TKIs in triple-negative breast cancer (TNBC)." (PMID 22788954, 2012).
heart failure (20 papers, 2008 to 2025). Inability of the heart to pump blood at an adequate rate to meet tissue metabolic requirements. "Based on high levels in the early phase of MI and in heart failure, HGF has been suggested as a prognostic and diagnostic biomarker of CV disease." (PMID 33439866, 2021). "Cardiac-failure-associated jaundiced sera containing higher level of HGF was optimized as a hepatogenic conditioned culture system for hMSCs trans-differentiation." (PMID 24642599, 2014). "Since there is marked increase in serum HGF level in this study, we hypothesize that HGF may play a key role as a prognostic biomarker of cardiac failure-associated jaundice (hyperbilirubinemia)." (PMID 24642599, 2014). "MET encoded a receptor tyrosine kinase c-MET for a hepatocyte growth factor (HGF), which was an important target of ginsenoside Rg5 against heart failure." (PMID 36313322, 2022). "Patients with NASH present an increase in growth factor (HGF) as well as those with advanced heart failure." (PMID 31547124, 2019). "Still, plasma from patients with advanced heart failure presents elevated levels of HGF." (PMID 31547124, 2019). "This implies that high HGF levels may indicate the decompensation of the body in heart failure." (PMID 40041176, 2025). "Hepatocyte growth factor (HGF) has well-documented pro-angiogenic roles in post-ischemic and post-infarcted heart failure models as well." (PMID 33918396, 2021). "Investigators found significantly higher stem cell growth factor beta (SCGF beta), hepatocyte growth factor (HGF), monokine induced by interferon gamma (CXCL9), and macrophage inhibitory factor (MIF) in Chagas myocardiopathy patients with advanced heart failure compared to the control group." (PMID 38133693, 2023). "Bone marrow-derived MSCs (BM-MSCs) are important for the formation of hematopoietic stem cell niche and are a promising cell source for regenerative medicine for heart failure or cerebral infarction because they express various paracrine factors such as VEGF and HGF." (PMID 32070429, 2020).